CCDC13 (coiled-coil domain containing 13)
Description:
Required for primary cilia formation and promotes the localization of the ciliopathy protein BBS4 to both centriolar satellites and cilia.
Synonyms: FLJ25467
Tractability: PROTAC: ubiquitination databases record sites on it.
Gene: Protein-coding gene on chromosome 3 (42,705,756 to 42,773,253, reverse strand). Ensembl gene ENSG00000244607.
Subcellular location: Cytoplasm, cytoskeleton, microtubule organizing center, centrosome, centriolar satellite; Cytoplasm, cytoskeleton, cilium basal body
Subcellular location (Human Protein Atlas): Basal body; Centriolar satellite; Cytosol; Nucleoplasm
Gene Ontology:
Molecular function: protein binding; microtubule binding
Biological process: cytoplasmic microtubule organization; DNA damage response; non-motile cilium assembly; axoneme assembly
Cellular component: centriolar satellite; centrosome; axonemal central pair
Genetic constraint (gnomAD): Loss-of-function variants: 64 observed, 87.03 expected, observed/expected ratio (o/e) 0.74, 90% interval 0.6 to 0.91. The upper end of that interval is the gene's LOEUF score, 0.91, which puts it in group 3 of 6, group 1 being the genes least tolerant of losing a copy. Missense variants: 820 observed, 891.59 expected, observed/expected ratio (o/e) 0.92, 90% interval 0.87 to 0.97. Synonymous variants: 307 observed, 364.07 expected, observed/expected ratio (o/e) 0.84, 90% interval 0.77 to 0.93.
Homologues: Orthologues: chimpanzee CCDC13 (99% identical), macaque CCDC13 (96% identical), pig CCDC13 (84% identical), dog CCDC13 (84% identical), rat Ccdc13 (77% identical), mouse Ccdc13 (77% identical), guinea pig CCDC13 (72% identical), tropical clawed frog ccdc13 (49% identical), zebrafish ccdc13 (38% identical), Drosophila melanogaster CG13032 (21% identical).
Diseases named in the same sentence as CCDC13 in open-access papers:
CCDC13 is named in the same sentence as 6 diseases in open-access papers, as found by Europe PMC text mining. Sharing a sentence is not in itself a finding about the gene and the disease. The quoted sentences say what the papers report.
male infertility (3 papers, 2025). The inability of the male to effect fertilization of an ovum after a specified period of unprotected intercourse. "Using knockout mouse models, we demonstrated that Ccdc13 deficiency led to male infertility with multiple morphological abnormalities of the sperm flagella (MMAF)-like phenotype due to defects in sperm flagellum biogenesis." (PMID 40585997, 2025). "Disruption of Ccdc13 in Drosophila results in the complete loss of CP MTs in sperm flagella, leading to male infertility due to immotile sperm." (PMID 40492112, 2025). "Thus, knockout of Ccdc13 causes severe sperm flagellar malformation, leading to male infertility." (PMID 40585997, 2025). "Several satellite genes have been associated with male infertility and sperm flagellum defects in humans and mice, including PCM1, CEP131, BBS4, OFD1, CEP290, CCDC13, etc.." (PMID 40801568, 2025). "The knockout of the Ccdc13 gene led to hydrocephalus and male infertility, accompanied by severe defects in the formation of ependymal cilia and sperm flagella." (PMID 40585997, 2025).
Hydrocephalus (2 papers, 2025). Hydrocephalus is an active distension of the ventricular system of the brain resulting from inadequate passage of CSF from its point of production within the cerebral ventricles to its point of absorption into the systemic circulation. "Ccdc13 deficiency in mice leads to the loss of central MTs in motile ependymal cilia, resulting in abnormal cilia motility and hydrocephalus." (PMID 40492112, 2025). "Similarly, knockout of Ccdc13 in mice causes defects in the CP of brain ependymal cilia, resulting in abnormal ciliary beating and hydrocephalus." (PMID 40492112, 2025). "Ccdc13-/- mice in the C57BL/6J background exhibited severe hydrocephalus and were markedly smaller than their littermate controls, resulting in lethality within 10 days after birth." (PMID 40585997, 2025).
ciliopathy (1 paper, 2025). A genetic disorder of the cellular cilia or the cilia anchoring structures, the basal bodies, or of ciliary function. "Given the critical involvement of Ccdc13 and Spef1 in motile cilia function, it would be of great interest to explore whether mutations in these genes contribute to ciliopathies." (PMID 40492112, 2025). "Furthermore, understanding how Ccdc13 and Spef1 interact with other ciliopathy-related proteins could reveal deeper insights into the molecular basis of motile cilia dysfunction, with significant implications for the development of targeted clinical therapies." (PMID 40492112, 2025).
uterine disease (1 paper, 2025). "In cattle, the higher levels of expression of CCDC13, CCDC65, and AK7 genes in healthy cows compared to those with uterine disease is consistent with their expression in subfertile heifers in our study." (PMID 41300775, 2025).
CCDC13 also shares sentences with these, for which no sentence is quoted: congenital hydrocephalus (1 paper); periodontitis (1).